SEMA3F (semaphorin 3F)
Description:
May play a role in cell motility and cell adhesion.
Synonyms: SEMAK; Sema4; SEMA-IV
Tractability: Antibody: UniProt places it where antibodies can reach, with medium confidence; UniProt predicts a signal peptide or a membrane-spanning region; its Gene Ontology location is reachable by antibodies, with medium confidence.
Gene: Protein-coding gene on chromosome 3 (50,155,012 to 50,189,075, forward strand). Ensembl gene ENSG00000001617.
Subcellular location: Secreted
Gene Ontology:
Molecular function: chemorepellent activity; neuropilin binding; semaphorin receptor binding
Biological process: axon guidance; axon extension involved in axon guidance; branchiomotor neuron axon guidance; facial nerve structural organization; negative chemotaxis; nerve development; neural crest cell migration; positive regulation of cell migration; semaphorin-plexin signaling pathway; sympathetic ganglion development; sympathetic neuron projection extension; sympathetic neuron projection guidance; trigeminal nerve structural organization; neural crest cell migration involved in autonomic nervous system development; regulation of postsynapse organization; system development; ventral trunk neural crest cell migration
Cellular component: extracellular region; plasma membrane; glutamatergic synapse
Genetic constraint (gnomAD): Loss-of-function variants: 30 observed, 97.81 expected, observed/expected ratio (o/e) 0.31, 90% interval 0.23 to 0.42. The upper end of that interval is the gene's LOEUF score, 0.42, which puts it in group 1 of 6, group 1 being the genes least tolerant of losing a copy. Missense variants: 848 observed, 1,121.5 expected, observed/expected ratio (o/e) 0.76, 90% interval 0.71 to 0.8. Synonymous variants: 366 observed, 437.9 expected, observed/expected ratio (o/e) 0.84, 90% interval 0.77 to 0.91.
Homologues: Orthologues: chimpanzee SEMA3F (99% identical), macaque SEMA3F (98% identical), dog SEMA3F (97% identical), rat Sema3f (96% identical), guinea pig SEMA3F (95% identical), pig SEMA3F (94% identical), rabbit SEMA3F (94% identical), mouse Sema3f (93% identical), tropical clawed frog sema3fl (75% identical), zebrafish sema3fb (69% identical), zebrafish sema3fa (68% identical). Paralogues in human: SEMA3C (51% identical), SEMA3A (46% identical), SEMA3B (44% identical), SEMA3D (43% identical), SEMA3E (43% identical), SEMA3G (41% identical), SEMA4D (28% identical), SEMA4C (28% identical), SEMA4B (28% identical), SEMA5B (28% identical), SEMA4G (27% identical), SEMA4A (26% identical), and 7 more.
Diseases named in the same sentence as SEMA3F in open-access papers:
SEMA3F is named in the same sentence as 87 diseases in open-access papers, as found by Europe PMC text mining. Sharing a sentence is not in itself a finding about the gene and the disease. The quoted sentences say what the papers report.
breast carcinoma (14 papers, 2008 to 2024). "Reduced levels of RORα and SEMA3F have been found to be linked to poor clinical outcomes in human breast cancer cells; however, RORα activation suppresses aggressive phenotypes, tumor invasion, and growth of breast cancer cells in vivo." (PMID 39518891, 2024). "The genes for semaphorins 3B and 3F (SEMA3B and SEMA3F) are located at chromosome 3p21.3, which is a site of frequent allelic loss and acquired promoter methylation in breast cancer, resulting in the loss of gene expression, implicating them as tumour suppressors." (PMID 37685898, 2023). "We revealed SEMA3F as a promoter of invasion during the DCIS-to-invasive ductal carcinoma transition in breast cancer (BC) through the action of NRP1 and NRP2." (PMID 39138514, 2024). "SEMA3F enables the transition from an epithelial breast cancer phenotype to a mesenchymal phenotype, promoting invasive traits and initiating noninvasive to invasive transition." (PMID 39138514, 2024). "By contrast, SEMA3F and its receptor, NRP-2, have roles in cell migration; for example, SEMA3F gradients had repulsive effects on the migration of thymocytes and the highly motile C100 breast cancer cells —an effect that was blocked by an anti-NRP-2 antibody." (PMID 37685898, 2023). "By contrast, SEMA3B had similar higher expression in normal-like, LumA, and LumB than in Her2 and Basal like tumours, and SEMA3F had significantly higher expression in Her2, LumA, LumB than in normal and basal type of breast cancer." (PMID 32241267, 2020). "Among them, a new SEMA3F transcript is expressed in all breast cell lines and breast cancer biopsies, and is translated into a new semaphorin 3F isoform." (PMID 26784191, 2016). "Among them, a new shorter SEMA3F alternative isoform, highly expressed in BC cell lines and breast cancer biopsies, was identified." (PMID 26784191, 2016). "Expression of RORα in breast cancer cells significantly induces SEMA3F transcription and inhibits the mammary tumor invasion in 3D culture." (PMID 23443091, 2012). "Intriguingly C100, a breast cancer cell line that expresses both Nrp1 and Nrp2, responds to exogenous Sema3f with inhibition of cell spreading, and this response is insensitive to the addition of anti-Nrp1 functional blocking antibody." (PMID 22783168, 2012). "The expression of SEMA3F was negatively correlated with overall survival in invasive BC patients with all breast cancer subtypes and in grade 1 (less aggressive) and grade 3 tumors (the most aggressive ones), denoting the importance of SEMA3F expression as a marker of poor survival." (PMID 39138514, 2024). "Besides this, ID4, SEMA3F, FOXD, KCNK5, WNK4 and ECM1 associate with chemoresistance origin and SOX5, ITM2A, SNCG, EPHA4, NTS, FGFR2 and ENPEP associate moreover with breast cancer tumorigenesis." (PMID 37239828, 2023). "For instance, although expressions of all SEMA3 genes are associated with a better prognosis based on the survival analyses in breast cancer, SEMA3E and SEMA3F was found to be associated with more aggressive HER2 and basal like molecular subtypes, indicating a tumor promoter role in those subtypes." (PMID 32241267, 2020). "Moreover, silencing SEMA3F expression in RORα-expressing breast cancer cells rescues the invasive phenotypes in 3D culture, suggesting that tumor suppressor function of RORα is at least partially conferred by SEMA3F." (PMID 23443091, 2012). "Thus, the concentration of recombinant sema3D found in the conditioned medium of either MDA-MB-231 breast cancer cells or in MDA-MB-435 melanoma cells was significantly lower than the concentrations of sema3F or sema3G." (PMID 18818766, 2008).
breast carcinoma (continued). "As Her2 and basal like breast cancer are the more aggressive types of tumours, higher gene expression in these subtypes may associate with poor prognosis, such as in the case of SEMA3E and SEMA3F." (PMID 32241267, 2020). "In vitro, exogenous Sema3f inhibits cell attachment and spreading in the breast cancer cell line MCF7, a line that expresses Nrp1 but not Nrp2; this inhibition is blocked by the addition of anti-Nrp1 functional blocking antibody." (PMID 22783168, 2012). "To put this prediction to the test we expressed sema3A and sema3F in MDA-MB-468 breast cancer cells, which do not express np1, np2 or PlexD1." (PMID 18818766, 2008).
lung carcinoma (12 papers, 2008 to 2024). "When the cDNA encoding sema3F was expressed in lung cancer cells, breast cancer cells or colorectal cancer cells it inhibited their anchorage-free proliferation and invasiveness." (PMID 30696103, 2019). "In lung cancer cells, anti-tumor effect of Sema3F is associated with loss of activated α5β3 integrin." (PMID 24212788, 2011). "Indeed, deletions occur in the region 3p21.3 of the short arm of chromosome 3, a region encoding for Sema3B and Sema3F in various cancers, including lung cancer and even ovarian cancer." (PMID 24212788, 2011). "Here, SEMA3F expression resulted in decreased intratumoral microvessel density in lung cancer models in mice." (PMID 39232098, 2024). "Among these, the negative regulation of HIF-1α/VEGF axis, tumor growth and microvessel density in lung cancer has been reported when Sema3F was overexpressed." (PMID 33858502, 2021). "In H157 lung cancer cells, sema3F inhibited multiple signaling pathways including Protein kinase B (AKT)/Signal transducer and activator of transcription 3 (STAT3) signaling resulting in the loss of activated αvβ3-integrin." (PMID 30696103, 2019). "Sema3F was also identified as a tumor suppressor of lung cancer and, subsequently, was identified as an inhibitor of the progression of additional types of cancer." (PMID 30696103, 2019). "For example, semaphorin 3B (SEMA3B) and 3F (SEMA3F) were initially identified as tumor suppressors in lung cancer, because small cell lung cancer is correlated with a deletion in the short arm of chromosome 3 (3p21)." (PMID 30532711, 2018). "In lung cancer cells, consistent with our results, SEMA3F downregulates the hypoxia-inducible factor-1α (HIF-1α) protein and VEGF mRNA levels by blocking the Akt-mTOR signaling pathway." (PMID 30532711, 2018). "The first evidence for a tumor suppressor effect came from lung cancer, in which the region of chromosome 3p21 containing SEMA3F coding gene are commonly deleted." (PMID 26447612, 2015). "Among them, semaphorin 3F (SEMA3F) was first described as a tumor suppressor in lung cancer where its expression is lost with the deletion of 3p21.3 region." (PMID 26447612, 2015). "Although SEMA3F and SEMA3B are generally regarded as tumor suppressors and methylated SEMA3F has been reported in lung cancers, it is neo-expression instead of suppression of SEMA3/Plexin expression that is generally observed in PDACs." (PMID 23251334, 2012). "Indeed, sema3F and sema3B have been characterized as bona fide tumor suppressors of lung cancer, and sema3A has been found to function as an endogenous angiogenesis inhibitor that is down-regulated during tumor progression." (PMID 30696103, 2019). "Several groups, including ours, have demonstrated that SEMA3F inhibits tumor growth, angiogenesis and metastasis in various tumors, such as melanoma, osteosarcoma, ovarian cancer, colon cancer, and lung cancer." (PMID 30532711, 2018). "First observations that Semaphorin 3F (Sema3F) might have a role in cell motility and cell invasion was suggested by Brambilla and colleagues, in lung cancer cells." (PMID 24212788, 2011). "In addition, we showed that SEMA3F protein correlated negatively with VEGF in lung cancer, and recently demonstrated that SEMA3F reduced VEGF mRNA level and HIF-1α protein level." (PMID 18781179, 2008). "SEMA3F also inhibits Akt-mTOR signaling in several other cell lines expressing NRP2, including lung cancer cells, melanocytes, Jurkat T lymphocytes, and ECs." (PMID 30532711, 2018). "In contrast, the level of SEMA3F (semaphorin 3F), a secreted semaphorin with potent antitumor activity that binds NRP2, was decreased in a ZEB1-induced EMT lung cancer model." (PMID 28672805, 2017). "In addition, SEMA3F expression is downregulated by ZEB-1, an E-box transcription repressor in lung cancer." (PMID 30532711, 2018).
lung carcinoma (continued). "When nude rats were orthotopically implanted with lung cancer cells transfected or not with Sema3F gene, all animals injected with cells expressing sema3f survived to 100 days whereas all the other rats died." (PMID 24212788, 2011).
epilepsy (8 papers, 2008 to 2025). A brain disorder characterized by episodes of abnormally increased neuronal discharge resulting in transient episodes of sensory or motor neurological dysfunction, or psychic dysfunction. "In addition, we identified a number of genes altered in PTE+ astrocytes that are known to be involved in differentiation, migration, and cell morphology, of which several are associated with epilepsy (i.e., Eml1, Map2, Map1b, Sema3f, and Ptn)." (PMID 37174647, 2023). "Overall, studies in knock-out mice suggest that Sema3F signaling may be implicated in the etiology of epilepsy." (PMID 34045951, 2021). "Interestingly, 10–20% of individuals with the fragile X syndrome also develop epilepsy, raising the possibility that dysregulation of Sema3F predisposes humans to epilepsy as well." (PMID 34045951, 2021). "The chromosome 3 region spans 159 genes, including neuronal development genes SEMA3F and SEMA3B, and epilepsy-associated genes NPRL2, CACNA2D2, and CYB561D2." (PMID 35190550, 2022). "Mutant animal results suggested that Sema3F and its receptor Npn-2 play important roles in animal models of epilepsy." (PMID 36044155, 2022). "Direct functional evidence for a function of semaphorins and their receptors in epilepsy is supported by Sema3F knockout mice and some NRP2 mutant mice that are more prone to seizures." (PMID 18781179, 2008). "Given that Npn-2 expression persists in adult brains, especially in the hippocampus and the expression of Sema3F and Npn-2 change in mTLE patients and adult animal models of epilepsy, we ask whether it plays any role in epilepsy during adulthood." (PMID 36044155, 2022). "Also, the expression of Sema3F and Npn-2 changed significantly in mTLE patients and animal models of epilepsy." (PMID 36044155, 2022). "We aimed to investigate the expression of proteins that might relate to epilepsy—mammalian target of rapamycin (mTOR) and semaphorin 3F (SEMA3F), respectively—for establishing the mechanism and explaining the antiepileptic effect of GR." (PMID 32140643, 2020). "We are wondering if the expression level of Sema3F and Npn-2 could change during epilepsy." (PMID 36044155, 2022). "However, a role for Nrp2 (or Sema3F) in human epilepsy is currently unknown." (PMID 39578518, 2025). "Here, we uncovered a novel role of axon guidance molecule family Sema3F/Npn-2 signaling in MFS and epileptogenesis in a rat model of epilepsy." (PMID 36044155, 2022). "The Sema3F/NTP-2 family, for instance, modulates mossy fiber sprouting and affects seizure development, highlighting its important contribution to axon guidance in shaping neuronal connectivity and signal transmission in epilepsy." (PMID 40723903, 2025).
melanoma (8 papers, 2008 to 2022). A malignant, usually aggressive tumor composed of atypical, neoplastic melanocytes. "Even if Sema3F overexpressing tumors obtained after injection of melanoma cells in mice, presented similar volume, they were less vascularized and showed features of less aggressive tumors when compared to parental ones." (PMID 33858502, 2021). "While a general consensus for Sema3F as a tumor suppressor in melanoma has been reported, contradictory results were obtained regarding the effect of Sema3F on in vitro proliferation of melanoma cells." (PMID 33858502, 2021). "Sdf1, Sema3A and Sema3F are involved in melanoma, multiple myeloma, glioblastoma, neuroblastoma, pancreatic, prostate, ovarian and lung cancers." (PMID 30944331, 2019). "The expression of SEMA3F is consistently downregulated in highly metastatic tumor cells including the prostate, bladder, and melanoma cells in vitro and in vivo." (PMID 30532711, 2018). "In fact, in highly metastatic melanoma cells, Sema3F completely inhibits metastasis in vivo and decreased the number of intra-tumor vessels, suggesting that Sema3F has huge potential in anti-angiogenic and anti-metastasis therapies." (PMID 24212788, 2011). "MDA-MB-435 melanoma cells express predominantly np2, a receptor for sema3F and sema3G and very little if any np1." (PMID 18818766, 2008). "Similarly, Sema3F has primary functions as a tumor suppressor, inhibiting the attachment and metastatic spread of lung, breast, and melanoma cells." (PMID 36970722, 2022). "In addition, Sema3F can represent a powerful inhibitor of melanoma cell proliferation through its relation with NRP receptors." (PMID 24212788, 2011). "(A) Overexpression of SATB2 with TETon (iSATB2) in normal human epidermal melanocytes (HEMA-LP) and in SKMEL2, SKMEL28, and A375 melanoma cells is sufficient to induce transcriptional activation of SOX10, SNAI1/2, PDGFB, and SEMA3F mRNA." (PMID 33527896, 2021).
glioblastoma (7 papers, 2015 to 2025). The most malignant astrocytic tumor (WHO grade IV). "Through immunoprecipitation, we found that SEMA3F inhibits the association between mTOR, raptor and rictor in glioblastoma cells, suggesting an inhibitory effect on both mTORC1 and mTORC2, respectively." (PMID 30532711, 2018). "In another approach using an in vivo model, we injected glioblastoma cells into the skin of nude mice, and after 2 days, the mice received a single intravenous injection of adenovirus encoding human SEMA3F (Ad-3F) or a control adenovirus (Ad-Cont)." (PMID 30532711, 2018). "In summary, to develop SEMA3F-mimetic bsAb(s) as candidates for new anticancer therapy, we characterized SEMA3F signaling and activity in glioblastoma U-251 MG cells." (PMID 41391772, 2025). "Among genes whose high expression correlates with decreased survival in glioblastoma, we identified several components of the “matrisome” and associated factors (FAM20C, SEMA3F, ADAMTSL4, ADAMTS14, SERPINA5, and CRELD1)." (PMID 32488114, 2020). "It was demonstrated that expression of SEMA3A, SEMA3D, and SEMA3F proteins significantly inhibited angiogenesis process and the formation of subcutaneous tumors derived from glioblastoma cells U87MG." (PMID 33036421, 2020). "In glioblastoma cells, SEMA3F inhibits the phosphorylation of Akt (T308 and S473), Erk, mTOR, and S6K, the mTOR downstream molecule, via NRP2 and plexin A1 receptors." (PMID 30532711, 2018).
glioma (7 papers, 2008 to 2025). A benign or malignant brain and spinal cord tumor that arises from glial cells (astrocytes, oligodendrocytes, ependymal cells). "In contrast to Sema3A, in vitro data revealed that Sema3F inhibits glioma cell migration via RhoA inactivation by p190 RhoGAP." (PMID 23050142, 2012). "An interesting observation was that SEMA3C and SEMA3F were statistically more expressed in glial tumours from men than from women, suggesting a possible hormonal regulation of these genes." (PMID 18781179, 2008). "The mechanism of EGCG+HC may be through the downregulation of SEMA3A and SEMA3F transcript expression which may play some roles in inhibiting the glioma proliferation and halts invasion via Plexin A1 (PLXNA1) and B2 (PLXNB2) receptors." (PMID 35392560, 2022). "Frequent deletion of 3p21 in gliomas, where the Sema3F gene resides could abolish its effect in counteracting tumor cell motility." (PMID 23050142, 2012). "This is consistent with previous reports that SEMA3F forms a complex with NRP2 and PLXNA1 within 5 min upon treatment on human glioma cells and induced the reduction in phosphorylation of downstream signaling molecules between 5 and 20 min." (PMID 41391772, 2025). "Moreover, to our knowledge, SEMA3D, SEMA3E, SEMA3F and SEMA3G expressions in human gliomas were not studied." (PMID 18781179, 2008).